SNORA70G (small nucleolar RNA, H/ACA box 70G)
Synonyms: U70G
Gene: Small nucleolar RNA gene on chromosome 12 (68,627,234 to 68,627,375, reverse strand). Ensembl gene ENSG00000206650.
Gene Ontology:
Biological process: RNA processing
Cellular component: nucleolus
Homologues: Orthologues: chimpanzee SNORA70 (94% identical), macaque SNORA70 (88% identical). Paralogues in human: SNORA70H (91% identical), SNORA70C (89% identical), SNORA70J (88% identical), SNORA70 (87% identical), SNORA70I (87% identical), SNORA70B (87% identical), SNORA70 (85% identical), SNORA70D (84% identical), SNORA70E (84% identical), SNORA70 (83% identical), SNORA70F (82% identical), SNORA70 (82% identical), and 14 more.